EDDM3A (epididymal protein 3A)
Description:
Possible function in sperm maturation.
Synonyms: HE3-alpha; FAM12A; HE3A; EP3A; HE3ALPHA; RAM1
Tractability: Antibody: UniProt places it where antibodies can reach, with high confidence; UniProt predicts a signal peptide or a membrane-spanning region; its Gene Ontology location is reachable by antibodies, with medium confidence. PROTAC: ubiquitination databases record sites on it.
Gene: Protein-coding gene on chromosome 14 (20,745,887 to 20,748,380, forward strand). Ensembl gene ENSG00000181562.
Subcellular location: Secreted
Gene Ontology:
Molecular function: protein binding
Biological process: sperm displacement
Cellular component: extracellular region
Genetic constraint (gnomAD): Loss-of-function variants: 1 observed, 0.16 expected, observed/expected ratio (o/e) 6.28. That is too few expected variants to judge how well the gene tolerates losing a copy. Missense variants: 199 observed, 187.25 expected, observed/expected ratio (o/e) 1.06, 90% interval 0.95 to 1.2. Synonymous variants: 75 observed, 63.78 expected, observed/expected ratio (o/e) 1.18, 90% interval 0.98 to 1.42.
Homologues: Orthologues: chimpanzee EDDM3A (99% identical), macaque EDDM3A (88% identical), rabbit RAM1 (54% identical), pig EDDM3B (50% identical), dog EDDM3B (48% identical), mouse Eddm3b (48% identical), rat Eddm3b (48% identical), rat LOC103693823 (48% identical). Paralogues in human: EDDM3B (69% identical).
Diseases named in the same sentence as EDDM3A in open-access papers:
EDDM3A is named in the same sentence as 5 diseases in open-access papers, as found by Europe PMC text mining. Sharing a sentence is not in itself a finding about the gene and the disease. The quoted sentences say what the papers report.
gastric cancer (1 paper, 2022). A primary or metastatic malignant neoplasm involving the stomach. "However, the role of EDDM3A in other types of human cancers, especially the underlying mechanism still unexplored, including gastric cancer (GC)." (PMID 35039478, 2022). "In summary, we show for the first time that EDDM3A expression is frequently upregulated in gastric cancer cells and its upregulation is closely associated with poor survival of GC patients." (PMID 35039478, 2022). "Our findings suggest EDDM3A as a potential prognostic marker and therapeutic target in the treatment of gastric cancer." (PMID 35039478, 2022). "In the present study, we explored the expression pattern, clinical significance and biological functions of EDDM3A in gastric cancer." (PMID 35039478, 2022). "Unexpectedly, we did not observe any significant direct interaction between EDDM3A and HIF-1, suggesting that HIF-1α is indirectly involved in the role of EDDM3A in gastric cancer cells." (PMID 35039478, 2022). "Here, we show that the expression of EDDM3A is significantly upregulated in gastric cancer (GC) tissues and its upregulation correlates with poorer survival in patients with gastric cancer." (PMID 35039478, 2022). "Significant upregulation of EDDM3A in GC implies that EDDM3A may exert a carcinogenic effect in gastric cancer." (PMID 35039478, 2022). "However, the role of EDDM3A in other types of human cancers, including gastric cancer (GC), is still unexplored." (PMID 35039478, 2022). "Therefore, we investigated the functional roles of EDDM3A in gastric cancer progression by knocking down or overexpression of EDDM3A in GC cells." (PMID 35039478, 2022).
non-small cell lung carcinoma (1 paper, 2022). A group of at least three distinct histological types of lung cancer, including non-small cell squamous cell carcinoma, adenocarcinoma, and large cell carcinoma. "A previous study in non-small cell lung cancer (NSCLC) has revealed that EDDM3A expression is upregulated in NSCLC tumor tissues as compared with matched adjacent non-tumor tissues and promotes cell proliferation of NSCLC." (PMID 35039478, 2022). "It has been demonstrated that EDDM3A expression is upregulated and promotes cell proliferation in non-small cell lung cancer (NSCLC)." (PMID 35039478, 2022).
tumor (2 papers, 2022). "To explore the roles of EDDM3A in GC, we first determined its expression in 30 GC tissues and paired adjacent non-tumor tissues using qRT-PCR analysis." (PMID 35039478, 2022). "Here, we demonstrate that the expression of EDDM3A is frequently increased in both tumor tissues and cell lines of GC, which is mainly due to the down-regulation of miR-618." (PMID 35039478, 2022). "Given that increased aerobic glycolysis plays an important roles in the promotion of tumor growth and metastasis, we therefore tested whether increased glycolysis contributes the promotion of GC growth and metastasis by EDDM3A in GC." (PMID 35039478, 2022). "Moreover, we found that the protein expression of EDDM3A was significantly correlated with the clinicopathological features of tumor size and lymphatic invasion." (PMID 35039478, 2022). "EDDM3A expression was significantly higher in GC tissues than adjacent non-tumor tissues." (PMID 35039478, 2022). "Mechanistically, enhanced aerobic glycolysis mediated by upregulation of HIF-1α and subsequently increased target glycolytic genes and decreased mitochondrial biogenesis was found to contribute to the promotion of tumor growth and metastasis by EDDM3A in GC cells." (PMID 35039478, 2022). "In addition, a significant negative correlation was also observed between the expression of miR-618 and EDDM3A in GC tumor tissues from 30 patients." (PMID 35039478, 2022). "In keeping with these findings, the protein expression of EDDM3A were also found to be significantly higher in tumor tissues of GC than in their adjacent non-tumor tissues, as evidenced by immunohistochemistry (IHC) staining in another 384 paired tumor and non-tumor tissues." (PMID 35039478, 2022).
cancer (1 paper, 2022). A tumor composed of atypical neoplastic, often pleomorphic cells that invade other tissues. "Our next question was whether EDDM3A is involved in the promotion of epithelial-mesenchymal transition (EMT), a key process driving cancer metastasis." (PMID 35039478, 2022).
EDDM3A also shares sentences with these, for which no sentence is quoted: endometriosis (1 paper).